HS6ST1 (heparan sulfate 6-O-sulfotransferase 1)
Description:
6-O-sulfation enzyme which catalyzes the transfer of sulfate from 3'-phosphoadenosine 5'-phosphosulfate (PAPS) to position 6 of the N-sulfoglucosamine residue (GlcNS) of heparan sulfate. Critical for normal neuronal development where it may play a role in neuron branching. May also play a role in limb development. May prefer iduronic acid.
Synonyms: HS6ST; HH15
Tractability: Antibody: its Gene Ontology location is reachable by antibodies, with high confidence; UniProt predicts a signal peptide or a membrane-spanning region.
Gene: Protein-coding gene on chromosome 2 (128,236,716 to 128,318,868, reverse strand). Ensembl gene ENSG00000136720.
Subcellular location: Membrane
Subcellular location (Human Protein Atlas): Nucleoplasm
Pathways (Reactome):
Metabolism: HS-GAG biosynthesis
Gene Ontology:
Molecular function: heparan sulfate 6-sulfotransferase activity; protein binding; sulfotransferase activity
Biological process: neuron development; heparan sulfate proteoglycan biosynthetic process
Cellular component: Golgi membrane; plasma membrane; Golgi apparatus; membrane
Genetic constraint (gnomAD): Loss-of-function variants: 4 observed, 21.76 expected, observed/expected ratio (o/e) 0.18, 90% interval 0.09 to 0.42. The upper end of that interval is the gene's LOEUF score, 0.42, which puts it in group 1 of 6, group 1 being the genes least tolerant of losing a copy. Missense variants: 300 observed, 466.2 expected, observed/expected ratio (o/e) 0.64, 90% interval 0.58 to 0.71. Synonymous variants: 189 observed, 203.33 expected, observed/expected ratio (o/e) 0.93, 90% interval 0.82 to 1.05.
Homologues: Orthologues: chimpanzee HS6ST1 (100% identical), macaque HS6ST1 (100% identical), dog HS6ST1 (99% identical), rat Hs6st1 (98% identical), mouse Hs6st1 (97% identical), pig HS6ST1 (97% identical), tropical clawed frog hs6st1 (82% identical), zebrafish hs6st1a (80% identical), zebrafish hs6st1b (78% identical), guinea pig HS6ST1 (69% identical), rabbit HS6ST1 (60% identical), Drosophila melanogaster Hs6st (43% identical), and 1 more. Paralogues in human: HS6ST3 (61% identical), HS6ST2 (60% identical).
Diseases named in the same sentence as HS6ST1 in open-access papers:
HS6ST1 is named in the same sentence as 38 diseases in open-access papers, as found by Europe PMC text mining. Sharing a sentence is not in itself a finding about the gene and the disease. The quoted sentences say what the papers report.
Kallmann syndrome (4 papers, 2014 to 2022). Kallmann syndrome (KS) is a developmental genetic disorder characterized by the association of congenital hypogonadotropic hypogonadism (CHH) due to gonadotropin-releasing hormone (GnRH) deficiency, and anosmia or hyposmia (with hypoplasia or aplasia of the olfactory bulbs). "Guided by our work with C. elegans, we have previously identified mutations in the HS 6-O-sulfotransferase HS6ST1 in patients with Kallmann syndrome/idiopathic hypogonadotrophic hypogonadism." (PMID 25098771, 2014).
hypogonadotropic hypogonadism (3 papers, 2012 to 2025). Abnormal ovarian or testicular function due to insufficient hormonal stimulation from the hypothalamic-pituitary axis. "Moreover, HS6ST1 gene mutations have recently been associated with idiopathic hypogonadotrophic hypogonadism, thereby increasing the evidence for a possible role of these two isoforms in gonadal fertility." (PMID 22794123, 2012). "Although we identified rare or novel missense variants in several hypogonadotropic hypogonadism genes (e.g. FGF17, HS6ST1, KISS1R, CHD7, IL17RD) definitively linking them to the PSIS phenotype is premature." (PMID 38096238, 2023).
metastatic tumors (3 papers, 2015 to 2018). "Regarding the enzymes responsible for the modificaton of the HS chains, alterations were only found in non-metastatic tumors, affecting N-sulfation and the isoforms HS6ST1, HS3ST3B and HS3ST5." (PMID 26482785, 2015). "Interestingly, alterations were found in only non-metastatic tumors, affecting N-sulfation, and the isoforms of heparan sulfate 6-O-sulfotransferase 1 (HS6ST1), heparan sulfate-glucosamine 3-sulfotransferase 3B1 (HS3ST3B1) and heparan sulfate-glucosamine 3-sulfotransferase 5 (HS3ST5)." (PMID 30197623, 2018).
cartilage tumor (2 papers, 2021 to 2023). "Prior studies revealed that the augmentation of 6-O-sulfation via three HS 6-O-sulfotransferases (HS6ST1-3) may promote the cartilage tumor progression." (PMID 36622753, 2023). "The increased expression of HS6ST1 mRNA during the progression of cartilage tumors suggests that HS6ST1 may promote the formation of malignant phenotypes of cartilage tumors." (PMID 34796198, 2021).
emphysema (2 papers, 2020 to 2022). "Importantly, administration of FGF10 rescued glycocalyx impairment and emphysema in a murine model of COPD, probably through a FGFR1/ERK/SOX9/HS6ST1 loop in endothelial cells." (PMID 36183124, 2022).
ovarian carcinoma (2 papers, 2007 to 2013). A malignant neoplasm originating from the surface ovarian epithelium. "In ovarian cancer, HS6ST1 and HS6ST2 were found to be strongly expressed by tumor cells, although only HS6ST1 was detected in endothelial cells." (PMID 24649258, 2013).
chondrosarcoma (1 paper, 2018). A malignant cartilaginous matrix-producing mesenchymal neoplasm arising from the bone and soft tissue. "They showed increased HS6ST1 and HS6ST2 expression during chondrosarcoma progression." (PMID 30544937, 2018).
cystic fibrosis (1 paper, 2023). Autosomal recessive disorder caused by pathogenic variants in the CFTR gene (cystic fibrosis transmembrane conductance regulator), which encodes a chloride and bicarbonate channel expressed in epithelial cells, and follow the diagnosis criteria. "Interestingly, HS6ST1 and RFFL have been associated with lung diseases, namely idiopathic pulmonary fibrosis and cystic fibrosis, respectively." (PMID 37686257, 2023).
Delayed puberty (1 paper, 2020). Passing the age when puberty normally occurs with no physical or hormonal signs of the onset of puberty. "However, recently, next-generation sequencing analysis has led to the discovery of new genes (i.e., IGSF10, HS6ST1, FTO, and EAP1) that are implicated in determining isolated self-limited delayed puberty in some families." (PMID 32508745, 2020).
Ewing sarcoma (1 paper, 2022). A small round cell tumor that lacks morphologic, immunohistochemical, and electron microscopic evidence of neuroectodermal differentiation. "Specifically, we found upregulation of enzymes involved in the catabolism of heparan sulfate proteoglycans (including SGSH, GNS, HS3ST4, HS3ST1, HS2ST1, and HS6ST1) in human Ewing sarcoma." (PMID 35285802, 2022).
glioblastoma multiforme (1 paper, 2017). "The expression of HS biosynthetic enzymes, including HS6ST1–3, has been shown to be predominantly down-regulated in glioblastoma, with the striking exceptions of HS3ST3a1 and the extracellular HS modifying enzyme HPSE." (PMID 29104277, 2017).
neuroblastoma (1 paper, 2022). Neuroblastoma (NB) is the most common solid, extracranial childhood tumor. "We used Neuro 2a cells, a widely used mouse neuroblastoma cell line that expresses high levels of Hs6st1 and low levels of the other Hs6st genes." (PMID 35899427, 2022).
Onset (1 paper, 2019). The age group in which disease manifestations appear. "In particular, in three patients presenting with mild, adult-onset disease we found variants (PROKR2 R85H, FGF8 P26L, and HS6ST1 R382W) already reported to impair protein activity in several functional characterization or to segregate with the phenotype, or both." (PMID 30669598, 2019).
osteoarthritis (1 paper, 2023). A noninflammatory degenerative joint disease occurring chiefly in older persons, characterized by degeneration of the articular cartilage, hypertrophy of bone at the margins and changes in the synovial membrane. "Alternatively, six of the top concordant genes (HTR7, TRAK1, LAMA4, HS6ST1, PDE4A, GPNMB) at 52 weeks have been documented in prior osteoarthritis literature." (PMID 37134114, 2023).
Stroke (1 paper, 2023). Sudden impairment of blood flow to a part of the brain due to occlusion or rupture of an artery to the brain. "The association between HS6ST1, TMEM132E, RFFL, and atherothrombotic stroke is less clear." (PMID 37686257, 2023).
type 2 diabetes (1 paper, 2020). "Not only abnormal metabolism of HS has been reported in DKD, but also variants in a gene encoding another HS-O sulfotransferase (HS6ST1) were associated with albuminuria in type 2 diabetes patients." (PMID 32425885, 2020).
vasculitis (1 paper, 2022). "rhTM promotes the expression of HS6ST1, a synthetic enzyme of heparan sulfate, in the LPS-induced vasculitis model in the lungs, while the present study suggests that it promotes the synthesis of glypican, which is present in the vascular endothelium." (PMID 36353180, 2022).
tumor (5 papers, 2007 to 2021). "Up to now, there are few reports on the association between EIF5A2, HGD, HS6ST1, PLS1, PTHLH, and YEATS2 methylation modification and tumor." (PMID 34796198, 2021). "These enzymes were strongly expressed by tumour cells, but only HS6ST1 was found in endothelial cells." (PMID 17437011, 2007). "Pearson Correlation Analysis of gene expression among the 21 tumor samples revealed that EXT1 showed strong correlation to all the other enzymes (r > 0.8 for EXT2, NDST1, and HS6ST1)." (PMID 33585200, 2020).
cancer (2 papers, 2021 to 2022). A tumor composed of atypical neoplastic, often pleomorphic cells that invade other tissues. "Interestingly, six genes, including ALS2, DAPL1, HS6ST1, IGFBP2, MGC12982, PPIAL4C, are selected in all predictions, i.e., when no samples is removed, or one cancer type data is removed." (PMID 35349572, 2022).
neurological diseases (1 paper, 2013). "Seven (12.7%) of the DEGs were associated with neurological diseases (BAT3, HS6ST1, IFI44L, RFC3, RPS9, STRC and TCF19) according to the IPA analysis (p = 0.003)." (PMID 23593218, 2013). "Remarkably, about 13% of the DEGs in FGF2 treated S252W fibroblasts were associated with neurological diseases (BAT3, HS6ST1, IFI44L, RFC3, RPS9, STRC and TCF19)." (PMID 23593218, 2013).
HS6ST1 also shares sentences with these, for which no sentence is quoted: acute myeloid leukemia (1 paper); anaplastic astrocytoma (1); astrocytoma (1); autism (1); brain cancer (1); cognitive disorder (1); congenital hypogonadotropic hypogonadism (1); COVID-19 (1); glioma (1); Hepatic failure (1); hypogonadism (1); idiopathic pulmonary fibrosis (1); lung diseases (1); Noonan syndrome (1); osteosarcoma (1); prostate carcinoma (1); puberty (1); retinal disease (1).